MUC16 (mucin 16, cell surface associated)
Diseases named in the same sentence as MUC16 in open-access papers (continued):
Sharing a sentence is not in itself a finding about the gene and the disease.
tumor (continued). "Previous research also found MUC16 had a higher mutation frequency in SKCM patients, which affect immune-related pathways and tumor-infiltrating immune cells resulting in better prognosis." (PMID 40066453, 2025). "The membrane-distal region (MDR), which binds to MUC16, is represented by region I. The MSLN MDR has emerged as the primary target for current immunotherapy approaches because of the role the MSLN–MUC16 relationship plays in tumor development." (PMID 40227645, 2025). "BITEs targeting the tumor-retained portion of MUC16/CA125 have recently been described and are in early-phase clinical trials." (PMID 41413213, 2025). "The trial includes exploratory endpoints such as the evaluation of baseline tumor MUC16 expression by immunohistochemistry and other biomarkers as potential predictors of response." (PMID 41211166, 2025). "Ubamatamab (REGN4018) is an MUC16 x CD3 BiTE that crosslinks MUC16-expressing tumor cells with CD3-expressing T cells, thus promoting T cell–mediated cytotoxic activity." (PMID 40565299, 2025). "Another MUC16-targeting agent currently under investigation is REGN5668 (R5668), a bsAb designed to simultaneously bind MUC16 on tumor cells and CD28 on T-cells, thereby providing a co-stimulatory signal to enhance T-cell activation in the TME." (PMID 41211166, 2025). "MUC16 (CA125) is a well-known tumor biomarker utilized in OC screening and is recognized for its immunosuppressive effects by interacting with the Siglec-9 receptor on NK cells, B cells and monocytes." (PMID 40255615, 2025). "No contrast enhancement was observed in any of the mice administered huIgG–Gd–DTPA, suggesting that huAR9.6 mediated that detection of MUC16-expressing cells within the tumor in the huAR9.6–Gd–DTPA cohort." (PMID 40149293, 2025). "In a reconstituted human lymphoma mouse model, NAV-006 demonstrated significantly improved anti-tumor activity compared to rituximab in the presence of human CA125/MUC16." (PMID 40583906, 2025). "The RT‐qPCR analysis revealed that all target genes (MUC3A, MUC4, MUC13, and MUC16) are significantly overexpressed in tumor samples as compared to control samples." (PMID 41142718, 2025). "The restricted expression of MUC16, or CA125, to the minor clone also has implications for the effect of tumor heterogeneity on clinical diagnostic testing." (PMID 41279090, 2025). "Neoantigens generated by MUC16 mutations can activate CD8 + T cells and enrich various tumor‐infiltrating immune cells to promote tumor immunity." (PMID 40022576, 2025). "MUC16 plays a predominant role in PDAC by influencing tumor microenvironment that promotes tumorigenesis and metastasis." (PMID 41142718, 2025). "Meanwhile, therapies targeting the MUC16 antigen successfully inhibited tumor growth in a mouse model by modifying the CAR to target its extracellular domain." (PMID 40969260, 2025). "It has been shown to inhibit intraperitoneal ovarian tumors in preclinical studies and inhibit MUC16-expressing murine tumor cell growth." (PMID 40565299, 2025). "On the one hand, MUC16 can inhibit tumor immunity by binding to inhibitory receptors on the surface of immune cells such as natural killer (NK) cells and macrophages." (PMID 40022576, 2025). "Mucins, including MUC1 and MUC16, are overexpressed in various gastrointestinal cancer types, and one of the key mechanisms by which they promote tumor survival is through immune evasion, effectively providing “protection” from immune cell-mediated killing." (PMID 41383589, 2025). "Clinical studies have demonstrated that the co-expression of MSLN and MUC16 is significantly correlated with tumor progression, adversely affecting patient prognosis." (PMID 41400642, 2025). "Cognate chemokine receptors were subsequently co-expressed in second generation CD28-costimulated CAR-T cells targeting the retained portion of the tumor associated antigen Muc16/CA125 (4H11) and evaluated for tumor-directed trafficking in vitro and in vivo." (PMID 41424784, 2025).
tumor (continued). "Muc16 is anchored to the surface of tumor cells or epithelial cells by transmembrane regions and a short cytoplasmic tail." (PMID 38758220, 2024). "Conditionally replicating tumor adenovirus (CRAd) can package a 5kda DNA fragment upstream of the MUC16 promoter, enabling precise replication and cutting of CA-125 in cancer cells." (PMID 38758220, 2024). "Key markers for alveolar dysfunction include Krebs von den Lungen-6 (KL-6), mucins (MUC-1, MUC-4, MUC-5, MUC-16), tumor markers (CA 15-3, CA 125, CA 19-9), surfactant proteins (Sp-A, Sp-D), and club cell secretory protein (CC16)." (PMID 39682582, 2024). "MUC16 is often overexpressed in tumors, and highly expressed MUC16 promotes tumor progression through various mechanisms." (PMID 38758220, 2024). "The roles and potential of MUC1 and MUC16 in tumor immunotherapy research have garnered widespread attention, especially their application as biomarkers in various cancer treatment strategies." (PMID 38361923, 2024). "Based on these results, we suggest that MUC16 regulates tumor growth at least in part by activating the PI3K/AKT pathway." (PMID 38758220, 2024). "Knockdown of ELF3 in C666-1 cells slowed down tumor growth and reduced tumor burden, whereas overexpression of MUC16 promoted tumor growth instead." (PMID 39219440, 2024). "For example, in EOC mice, PD1-anti-MUC16 CAR T cells showed stronger anti-tumor activity than single CAR T cells." (PMID 38758220, 2024). "This interaction triggers a series of events, including the activation, proliferation, and damaging effects of T cells against tumor cells that express MUC16." (PMID 38464532, 2024). "Although the level of MUC16 was high in tumor cells, we did find MUC16-positive fibroblast-like cells in tumor stroma areas." (PMID 39346763, 2024). "The first antibodies developed targeted the cleaved portion of Muc16, failing to detect the retained ectodomain on tumor cells." (PMID 39346763, 2024). "First, we examined the ability of H1L1, H1L2, H2L1, and H2L2 h4H11 antibodies to inhibit Matrigel invasion of MUC16-positive tumor cell lines; OVCAR3, OVCA-433, CAOV3." (PMID 38374055, 2024). "A majority of these tumor foci expressed MUC16, showing the potential ability to detect these residual tumor sections using intraoperative tools (NCT: 8/10; non-NCT: 8/11)." (PMID 39456534, 2024). "In this paper, the mechanism of action of MUC16 in the development of cancer, especially in the immune escape of tumor, is introduced in detail, indicating the potential of MUC16 in clinical treatment." (PMID 38758220, 2024). "MUC16 is expressed not only in tumor cells, but also in normal tissues, particularly in glands and epithelial cells." (PMID 38637885, 2024). "Abnormal expression of MUC16 promotes tumor progression through mesenchymal protein, PI3K/AKT pathway, JAK2/STAT3 pathway, ERK/FBW7/c-Myc, and other mechanisms, and plays an important role in the occurrence and development of tumors." (PMID 38758220, 2024). "The classic and most widely used tumor marker for HGSOC is CA125, a glycoprotein encoded by the MUC16 gene." (PMID 38275400, 2024). "In gastrointestinal tumor research, studies on MUC1 and MUC16 are crucial in unveiling tumor immune evasion mechanisms and progression." (PMID 38361923, 2024). "MUC16 can help recruit T cells and build a good anti-tumor immune microenvironment, which plays an important role in the immune process." (PMID 38758220, 2024). "Mutations in certain large genes, such as TTN, NEB, SYNE1, MUC16, and OBSCN, have previously been associated with tumor mutation burden (TMB)." (PMID 38473427, 2024).
tumor (continued). "MUC16 can directly inhibit NK cells in tumors through spatial distance and promote tumor progression." (PMID 38758220, 2024). "There was a significant correlation between MUC16 and tumor, node, metastases (TNM) stage and recurrence (P < 0.05), but not with patients’ sex, age, and smoking history (P > 0.05)." (PMID 39219440, 2024). "Of those matched adjacent tissues expressing MUC16, 15 out of 24 samples (62.5%) contained MUC16 expression in infiltrating tumor cells." (PMID 39456534, 2024). "Over-expression of the C-terminal 114 amino acids of MUC16 has been shown to promote transformation and tumor invasion in mouse models." (PMID 38225646, 2024). "In contrast, the RRGS-High subgroup is characterized by mutations in genes such as MUC16, PCLO, and CSMD3, which are commonly associated with more aggressive tumor features and poorer outcomes." (PMID 39668832, 2024). "Our study aimed to develop a highly sensitive and selective Ap-based SPR biosensor for detecting MUC16 tumor markers in blood serum by using DNA Ap as the targeting ligand of the MUC16 biomarker." (PMID 39206405, 2024). "PSA, CEA, and CA-125/MUC16 are frequently used cancer indicators, while exosomes, microRNA, and circulating tumor cells are emerging as a new source of biomarkers." (PMID 39184596, 2024). "Out of these 16 samples, 13 had no MUC16 expression (11 benign and 2 cancerous), while 3 expressed MUC16 (2 tumors and 1 tumor and benign tissue)." (PMID 39456534, 2024). "MUC16 overexpression has also been shown to facilitate tumor immune escape via direct suppression of natural killer (NK) and macrophages." (PMID 38374055, 2024). "Compared with 4H11 CAR-T cells alone, secreted ESK1 BiTE redirected additional T cells toward WT1 on tumor cells, resulting in improved anticancer activity against Muc16-overexpressing cancer cells." (PMID 38903506, 2024). "By contrast, proteases in the tumor microenvironment cleave away large portions of the MUC16 ectodomain, potentially uniquely exposing the 20aa membrane adjacent epitope for antibody binding in the context of cancer." (PMID 38225646, 2024). "Intriguingly, the aberrant expression of specific MUC proteins, notably Mucin 1 (MUC1) and Mucin 16 (MUC16), within tumor cells, is intimately associated with oncogenesis, proliferation, and metastasis." (PMID 38361923, 2024). "MUC16’s impact transcends tumor cells, prominently modulating the tumor environment by guiding the differentiation of CAFs." (PMID 38361923, 2024). "Our previous work highlighted the effectiveness of Gal3 inhibition in disrupting Mucin 16 (MUC16) induced tumor-promoting properties and its reduction improved overall survival in breast and ovarian xenograft models." (PMID 38438589, 2024). "Extensive research has established MUC1 and MUC16 as key players in cancer development, with expression patterns significantly influencing tumor progression and serving as vital prognostic markers." (PMID 38361923, 2024). "This study found that MUC16 expression was retained in the tumor following neoadjuvant chemotherapy treatment regimens." (PMID 39456534, 2024). "A recent study found that dual CAR‐T cells targeting both PDL1 and MUC16 exhibited enhanced anti‐tumour activity both in vitro and in vivo against OVCAR3 cells compared with single CAR‐T cells." (PMID 38800555, 2024). "In ex vivo tumor cultures that were obtained from patients with ovarian cancer, OAd-MUC16-BiTE, successfully overcame the immunosuppressive TME." (PMID 38464532, 2024). "Mouse mAb5E6 can improve drug efficacy by more accurately recognizing MUC16-CTER on the surface of tumor cells (the endogenous 114-amino acid carboxy-terminal fragment of MUC16 retained on the cell surface)." (PMID 38758220, 2024).
tumor (continued). "The OCOs faithfully inherited the molecular characteristics of the derived tumor tissues, with high MUC16 (CA125) expression verified by immunofluorescence under confocal microscopy and ELISA." (PMID 37644468, 2023). "As proof of principle study, we evaluated the anti-tumor potential of ch5E6 in MUC16- expressing pancreatic patient-derived tumor organoid for 5 days in real time using INCUCYTE live imaging system." (PMID 37567918, 2023). "There are few studies on the effect of MUC16 on neutrophils to regulate tumor immune microenvironment." (PMID 37644468, 2023). "The present study investigated multiple mutations identified from the selected fragments of MUC6 and MUC16 in the tumour and the surgical margin samples collected from the tonsillar tissue of OPSCC patients." (PMID 37504272, 2023). "The present study aimed to analyse the sequence of some selected fragments of MUC6 and MUC16 genes in the tumour and the margin samples obtained from the OPSCC patients." (PMID 37504272, 2023). "Previous studies have also shown that MUC16 functions in tumour proliferation, metastasis, and inhibition of natural killer cells to regulate the innate immune response." (PMID 36949429, 2023). "MUC16 showed significant co-expression with antigens (tumor-antigens & autoantigens) and acute phase reactants such as transglutaminases (TGM2), CEACAMs, C-Reactive Protein (CRP), and alkaline phosphatase (ALPP)." (PMID 36816942, 2023). "Using publicly available data, we perform molecular characterization of epithelial tumor cells and mesothelium derivatives in PDAC to decouple tumor-stromal regulation of MUC16." (PMID 36816942, 2023). "The hierarchical cluster analysis performed for the identified variants revealed no significant similarities nor mutation patterns in the MUC6 coding sequence or both MUC6 and MUC16 corresponding to the tumour or margin groups." (PMID 37504272, 2023). "As mesothelium is an abundant source of MUC16 and a major contributor to stromal heterogeneity in PDAC, we investigated the regulation of MUC16 in tumor and stromal compartments individually." (PMID 36816942, 2023). "The expression levels of hsa-miR-199a-5p, hsa-miR-214-3p, hsa-miR-424-5p, and hsa-miR-125b-5p were significantly and inversely correlated with the expression level of MUC16 mRNA in the tumor tissue and with the CA125 level in the blood serum." (PMID 37569592, 2023). "Mucine 16 (MUC16), a glycoprotein of the mucin family, is expressed in various tumor cells and is involved in the proliferation and metastasis of cancer cells." (PMID 36826026, 2023). "Future studies will be directed to evaluate the therapeutic efficacy of chimeric mAb5E6 in combination with standard-of-care therapies and elucidate the impact of MUC16 targeting in the context of the tumor microenvironment." (PMID 37567918, 2023). "In PDAC, the infiltrating tumor cells show high expression of MUC16 relative to matched PanIN‐3 cells, correlating with tumor size, serosal invasion, and lymph node metastasis." (PMID 36816942, 2023). "Lower risk scores were also correlated with higher immunophenotype scores, tumor mutation burden, and mutation rates in significantly mutated genes (e.g., FAT4 and MUC16)." (PMID 36755298, 2023). "MUC16 is the largest transmembrane mucin that plays an important role in metastasis, protecting tumor cells from cytotoxic reactions that occur when exposed to natural killer cells." (PMID 36833207, 2023). "We next performed a confocal analysis of MUC16 and HuR in the lung tumor xenografts and found that HuR distribution was higher in the cytoplasmic region in tumor tissues of scramble cells compared to MUC16 knockdown cells." (PMID 36918912, 2023).
tumor (continued). "Across these samples, MUC16 expression was merely limited to two epithelial tumor cell clusters, whereas expression of other mucins (like MUC1) was more uniformly distributed across the epithelial and SMC/myoepithelial cell clusters." (PMID 36816942, 2023). "Recent studies have revealed that MUC16 played an important role in Siglec-9-mediated tumor cell immune escape." (PMID 37644468, 2023). "MUC16 is involved in mediating the adhesion of free tumor cells, which is mainly achieved by interacting with mesothelin on mesothelial cells." (PMID 37377954, 2023). "The observed mutations of genes involved in antitumor immune responses were mostly polyclonal, but mutations in CSMD1, MUC16 and TTN occurred as clonal alterations, suggesting again a clonal advantage for those tumor cells." (PMID 36980598, 2023). "Among them, MUC1, MUC5AC, MUC4 and MUC16 are abnormally expressed in the early stages of PanIN, and the expression increases as the cancer progresses through carcinogenesis and tumor invasion." (PMID 37304241, 2023). "The present study aimed at the analysis of the sequence of selected MUC6 and MUC16 gene fragments in the tumour, as well as the margin, samples obtained from 18 OPSCC patients." (PMID 37504272, 2023). "MUC16, also known as cancer antigen 125 (CA125), consists of a repetitive epitope of mucin glycoprotein and has been implicated in cell proliferation and tumor promotion." (PMID 38067396, 2023). "For instance, it should be noted that in all patients, the largest number of genetic variants in both tumor and healthy tissue was found in the genes of the mucin family—MUC3A and MUC16." (PMID 36833207, 2023). "Intravenous or intraperitoneal injection of MUC16-CAR-T cells can delay the progression of OC or completely clear up the tumors in mouse tumor models." (PMID 36979400, 2023). "Decreased tumor cell migration and invasion upon deletion of MUC16 in T3M4 WT and SC cells highlight the tumorigenic potential of MUC16." (PMID 35628269, 2022). "In multivariate analysis, MUC16 (+) remained an independent risk factor for impaired survival as well as the known prognostic factor ECOG 1, multiple tumors, and the presence of tumor marker CA-19/9." (PMID 36230626, 2022). "We have previously demonstrated that the MUC16-targeting AR9.6 antibody robustly inhibits MUC16 dependent signaling and reduces the tumor burden in orthotopic mouse models of PDAC." (PMID 35628269, 2022). "This study demonstrates that the CRISPR/Cas9-mediated genetic deletion of MUC16 in PDAC cells decreases tumor cell migration." (PMID 35628269, 2022). "Associations between MUC16 mutations and TMB, microsatellite instability (MSI), LNM, and tumor microenvironment signatures were explored." (PMID 35211490, 2022). "Remarkably, genomic analysis suggested that the lower tumor mutation burden and gene mutation frequency (e.g., TTN, MUC16, and LRP1B) were found in the high-risk group patients." (PMID 35281096, 2022). "Due to its slow internalization, MUC16 is considered a poor therapeutic target for the immunoconjugates or ADCs that act inside tumor cells." (PMID 36559316, 2022).